RN7SKP221 (RN7SK pseudogene 221)
Gene: Miscellaneous RNA gene on chromosome 22 (21,545,344 to 21,545,644, reverse strand). Ensembl gene ENSG00000222352.
Homologues: Orthologues: chimpanzee 7SK (99% identical), guinea pig 7SK (62% identical). Paralogues in human: RN7SKP131 (99% identical), RN7SKP63 (99% identical), 7SK (79% identical), RN7SKP71 (79% identical), RN7SKP78 (77% identical), RN7SKP176 (77% identical), RN7SKP203 (77% identical), RN7SKP189 (76% identical), RN7SKP9 (76% identical), RN7SKP20 (75% identical), RN7SKP50 (75% identical), RN7SKP153 (75% identical), and 284 more.